IL6 (interleukin 6)
Diseases named in the same sentence as IL6 in open-access papers (continued):
Sharing a sentence is not in itself a finding about the gene and the disease.
atherosclerosis (continued). "Interleukin-6 (IL-6) as a cytokine plays an important role in the “response to injury” model of endothelial cells and atherosclerosis, and it is encoded and regulated by the IL-6 receptor (IL6R) gene, which is located in the chromosome 1q21." (PMID 38827573, 2024). "Evidence from genetic studies has demonstrated a potentially causal role of IL-6 in the development and the acceleration of atherosclerosis." (PMID 39077632, 2024). "For IL-6, a distinct homeostasis appears to be necessary to prevent atherogenesis: high levels of IL-6 are clearly connected to atherosclerosis, but on the other hand, atherosclerosis is enhanced in IL-6-deficient mice." (PMID 36178662, 2023). "Interleukin-6 (IL-6) is secreted following inflammasome activation and is implicated in the chronic inflammatory process of atherosclerosis." (PMID 36835838, 2023). "Elevated levels of C-reactive protein (CRP), interleukin-1 (IL-1) and interleukin-6 (IL-6) are associated with atherosclerosis and its complications, including plaque initiation, progression and rupture." (PMID 36830690, 2023). "Mice with experimental CHIP show increased pro-inflammatory drive of the NLRP3/IL-1β/IL-6 axis and atherosclerosis, and humans carrying a genetic deficiency in IL6 appear to have reduced cardiovascular risk related to CHIP." (PMID 37209535, 2023). "Since CRP mainly reflects themechanism underlying atherosclerosis, IL-6 is causally involved in this process.Experimental studies have shown that IL-6 contributes to initiation andprogression of atherosclerotic plaque." (PMID 39076864, 2023). "Among Black individuals within the Multi-Ethnic Study of Atherosclerosis, we evaluated associations of rs5491 with 3 inflammatory biomarkers (high-sensitivity C-reactive protein [hsCRP], interleukin-6 [IL-6], and tumor necrosis factor-α receptor 1 [TNFR-1])." (PMID 38074621, 2023). "CANTOS, a canakinumab anti-inflammatory thrombosis outcome study, demonstrated that inhibiting IL-1 and IL-6 can reduce the rates of cardiovascular events, especially IL-6, which is directly related to the risk of the occurrence of atherosclerosis." (PMID 37555019, 2023). "The role of IL-6 in the atherosclerotic process was demonstrated in apoE-deficient mice, where recombinant IL-6 injections worsened early atherosclerosis." (PMID 37893519, 2023). "A novel anti-IL-6 monoclonal antibody (ziltivekimab) was tested in patients with chronic kidney diseases who were at a high risk of developing atherosclerosis." (PMID 37298597, 2023). "Exogenous IL-6 in the apolipoprotein E-deficient (ApoE−/−) model of atherosclerosis increased the formation of atherosclerotic lesions, while the IL-6 receptor antibody downregulated inflammation and reduced atherosclerotic lesion sizes." (PMID 37049512, 2023). "It has also been shown that METTL14 promotes inflammatory responses in atherosclerosis-associated macrophages via NF-κB/IL-6 signaling." (PMID 37441706, 2023). "For example, both chronic administration and genetic deficiency of IL-6 have been reported to worsen atherosclerosis in ApoE knockout mice." (PMID 37018396, 2023). "In a study investigating atherosclerosis risk factors in schizophrenia patients, it was reported that biochemical parameters, such as P Selectin, IL-6, MCP-1, and CD 40L, which are markers of atherosclerosis, were elevated." (PMID 36836510, 2023). "It has been claimed that Lp(a) levels are elevated in patients with increased serum IL-6, which is most closely related to an increased risk of atherosclerosis." (PMID 37509461, 2023). "IL-6 is a pro-inflammatory cytokine with pleiotropic effects, linked to atherosclerosis development and plaque vulnerability." (PMID 36676179, 2023). "TNF and IL-6 are two proinflammatory cytokines associated with atherosclerosis, plaque development, and increased cardiovascular risk." (PMID 37664830, 2023).
atherosclerosis (continued). "For instance, miR-467b has been implicated in the regulation of atherosclerosis and secretion of the proinflammatory cytokines IL-6, IL-1β, and TNF, which are also knowingly dysregulated in CCC." (PMID 36972298, 2023). "CVDs, such as atherosclerosis, hypertension, cardiac fibrosis, and cardiomyopathy, are all linked to IL-6." (PMID 37637634, 2023). "On the other hand, IL-12 (p70), fractalkine, IL-6, and IL-3 are associated with atherosclerosis with stenosis below 70%, where IL-6 can promote endothelial dysfunction and fractalkine can contribute to the early stages of plaque development and mild stenosis." (PMID 37629267, 2023). "Previous studies showed, that TET2 or JAK2 clonal mutation increases IL-6 and IL-1β production in myeloid cells supporting accelerated atherosclerosis." (PMID 38138958, 2023). "The JAK2/STAT3 pathway is intimately linked to the IL-6 cytokine family, which plays a critical role in endothelial cell dysfunction during atherosclerosis." (PMID 35607519, 2022). "It is believed that lifetime deficiency of IL-6 breaks the balance of IL-6 and IL-10 and thus promotes the development of atherosclerosis." (PMID 35402550, 2022). "This condition, together with other inflammatory markers, such as IL-6, was also evaluated in the current study and has been associated with the pathogenesis of atherosclerosis." (PMID 35929900, 2022). "This study concluded that sVCAM-1 is a risk-factor for the progression of atherosclerosis in patients with RA and that IL-6 plays a role in mediating this." (PMID 36249997, 2022). "Subclinical atherosclerosis plaque occurrence in SSc patients was reported to be associated with smoking, higher blood pressure, impaired kidney function, high levels of IL-6, serum levels of vascular cell adhesion molecule 1 and with ACA." (PMID 35769143, 2022). "Inflammation can be associated with all stages in the development and progression of atherosclerosis; in fact, elevated values of certain inflammatory markers, including IL-6 and CRP have been associated with adverse prognosis in patients with atherosclerosis." (PMID 36078455, 2022). "It is reported that IL6 can regulate macrophage polarization controls atherosclerosis associated vascular intimal hyperplasia." (PMID 36338963, 2022). "Considering that atherosclerosis is a chronic inflammatory disorder, IL-6 levels are expected to be increased among individuals with sub-clinical atherosclerosis who are at greater risk for future MI." (PMID 36028849, 2022). "Studies in mice show that senescence is associated with increased production of IL-6 in arteries, which take part in the positive feedback loop with mitochondrial dysfunction of the vasculature to promote the development of atherosclerosis." (PMID 35642067, 2022). "Although IL-6 has been implicated in the pathogenesis of atherosclerosis, in vitro studies have demonstrated that the activation of α7-nAChRs attenuates the release of IL-6 by macrophages, and the level of IL-6 is increased in patients with CAS." (PMID 35096275, 2022). "Endothelial deletion of Il6 or Vcan (encoding versican), genes shown to be highly expressed in mice with atherosclerosis or MI, reduced hematopoiesis and systemic myeloid cell numbers in these conditions." (PMID 35747128, 2022). "Elevated levels of IL-6 were also found to be associated with an increased risk of atherosclerosis, even when other risk factors for CVD are controlled for." (PMID 34640478, 2021). "This study demonstrated the potential use of IL-6 as a risk factor for coronary atherosclerosis and as a therapeutic target for atherosclerosis." (PMID 34071276, 2021).
atherosclerosis (continued). "Dysregulated IL-6 activity is associated with pathologies involving chronic inflammation and autoimmunity, including atherosclerosis." (PMID 33786327, 2021). "Some reports stated that various extracts from PE cause inhibition of the production of TNF-α, IL-1β, and IL-6 in atherosclerosis or neuronal cellular model." (PMID 34712342, 2021). "The progression of CHIP-associated atherosclerosis is mediated by the signaling of IL-6 and activation of the inflammasome." (PMID 34072794, 2021). "In this direction, two large meta-analyses have shown the pivotal role of IL-6 in the onset and development of inflammation and associated risk for atherosclerosis and CAD." (PMID 34760045, 2021). "AGE/RAGE signaling induces the activation of multiple intracellular signaling pathways involving NADPH oxidase, protein kinases C and MAPK, enhancing NF-κ Bactivity to promote a variety of genes associated with atherosclerosis such as IL-6." (PMID 34692849, 2021). "Another study that compared Il6+/− mice to Il6−/− Apoe−/− mice and showed increased atherosclerosis in the homozygous vs. heterozygous Il6-deficient mice, accompanied by an increased blood cholesterol level." (PMID 33924019, 2021). "Both human observations and mouse experiments implicate IL-6 in abdominal aortic aneurysmal disease, a condition commonly associated with atherosclerosis." (PMID 33924019, 2021). "Among inflammatory markers, only serum IL6 levels presented significant associations with subclinical atherosclerosis, being inversely related with ABI (r = − 0.568, P < 0.0001) and positively related with CIMT (r = 0.558, P < 0.0001)." (PMID 34354161, 2021). "IL-6 has also recently shown a strong and independent association with atherosclerotic cardiovascular disease events in a multi-ethnic study of atherosclerosis including over 6000 participants." (PMID 32748207, 2021). "Inflammatory cytokines, such as tumor necrosis factor-α and interleukin-6, can enhance the differentiation of the macrophage and are responsible for the interaction between bone loss and atherosclerosis in RA patients." (PMID 34641970, 2021). "IL-6 is an upstream regulator and plays a central role in promoting downstream inflammatory response, the leading cause of atherosclerosis." (PMID 34957238, 2021). "Incidence rates (95% CI) and hazard ratios (95% CI) for the association of CRP, IL-6 and fibrinogen with incident atrial fibrillation: The multi-ethnic study of atherosclerosis (2000–2015)." (PMID 33765041, 2021). "Atherosclerosis, heart failure, and atrial fibrillation are well established to be associated with elevated inflammation markers including IL-6." (PMID 33211155, 2021). "Some studies show that IL-6 deficiency in atherosclerosis-prone apolipoprotein E-deficient mice can actually display increased atherosclerosis." (PMID 33924019, 2021). "Apremilast also inhibited the expression of tumor necrosis factor-α (TNF-α), interleukin-6 (IL-6), and interleukin-8 (IL-8), which are deeply involved in the chronic inflammatory response associated with atherosclerosis." (PMID 33052879, 2020). "It is known that AGE and IL-6 are associated with atherosclerosis and inflammation, and PTH has been shown to stimulate the expression of AGE and IL-6 mRNA and expression of AGE receptor proteins in endothelial cells." (PMID 32823917, 2020). "CT-1 deficiency in advanced atherosclerosis mediated regulation of paracrine factors, such as interleukin (IL)-3, IL-6, IL-9, IL-15, IL-27, CXCL5, MCP-3, MIP-1α and MIP-1β." (PMID 32238841, 2020). "The similar findings of the two independent genetic studies indicate a causal link between IL-6 signaling and atherosclerosis in humans." (PMID 32121175, 2020).
atherosclerosis (continued). "The IL-6 was an important proatherogenic inflammatory cytokine in the pathway toward atherosclerotic events and was related to atherosclerosis and clinical cardiovascular disease risk." (PMID 33029103, 2020). "In C57B1/6 mice and in apoE-deficient mice, injection of recombinant IL-6 at supraphysiological doses enhances atherosclerosis." (PMID 32121175, 2020). "Content of plasma IL-6 in diabetic was significantly correlated with the content of homocysteine, which also is an independent risk factor of atherosclerosis." (PMID 31341840, 2019). "Accumulating evidence suggests IL-6 is implicated in the progression of atherosclerosis and plays a key role in inducing VSMC migration and proliferation." (PMID 31817202, 2019). "Despite clinical data demonstrating an association between IL-6 and atherosclerosis, IL-6 has little role in the clinical setting due to the lack of a readily-available assay and issues related to biomarker stability and half-life." (PMID 30873416, 2019). "It is IL6 receptor “trans-signalling” that is thought to underlie the pro-inflammatory actions of IL6 in a variety of diseases, including atherosclerosis." (PMID 30414891, 2019). "Several biomarkers of systemic inflammation have been associated with endothelial dysfunction and atherosclerosis, for example, IL-6 and CRP have been inversely correlated with the thickness of the intima media of the carotid in RA patients." (PMID 30818887, 2019). "Compared to CTL, both CLO and TIC significantly decreased levels of interleukin-6 (IL-6), a proinflammatory cytokine associated with atherosclerosis." (PMID 31242230, 2019). "The exacerbated production of IL-6 is associated with a variety of autoimmune and inflammatory diseases and other conditions, such as atherosclerosis and acute myocardial infarction." (PMID 30804931, 2019). "In contrast to CRP, there are consistent reports from multiple studies indicating a causal effect of IL-6 signaling in atherosclerosis." (PMID 31672136, 2019). "IL-6 levels have been shown to correlate with endothelial dysfunction, arterial stiffness, and the extent of subclinical atherosclerosis linked to plaque initiation and destabilization." (PMID 31292433, 2019). "A combination of mCRP, nCRP, and oxLDL also causes a decrease in both TNF-α and IL-6 production in a macrophage model of atherosclerosis." (PMID 29706967, 2018). "The role of IL-6 seems to be dose-dependent: several studies have confirmed the pro-inflammatory effects of IL-6 in atherosclerosis models, but a complete loss of IL-6 increases plaque formation and serum cholesterol levels in ApoE−/− mice." (PMID 29467675, 2018). "IL-1β has been shown to be implicated in the pathogenesis of atherosclerosis and thrombosis by the downstream stimulation of IL-6 and C-reactive protein (CRP)." (PMID 30333009, 2018). "Adding to its biological impact, IL-6 trans-signaling has been implicated in the pathogenesis of conditions including atherosclerosis, hemorrhagic trauma, and inflammation-based CVD." (PMID 29367584, 2018). "Dietary supplementation of EGCG counteracted several adverse effects associated with vascular inflammation and atherosclerosis, including decreased secretion of inflammatory cytokines such as IL-6 and TNF-α." (PMID 29593532, 2018). "Increased levels of pro-inflammatory IL-6 are associated with atherosclerosis, vasculitis, MI and HF." (PMID 29367584, 2018). "This makes EPAC1 an interesting candidate therapeutic target for the treatment of diseases in which IL-6 signalling is heavily implicated, such as atherosclerosis." (PMID 29367551, 2017). "Previous studies have showed that increasing levels of IL-18 and IL-6 have been found to be involved in the pathogenesis of atherosclerosis and associated with future CV events and mortality." (PMID 28474577, 2017).
atherosclerosis (continued). "Our data provide solid evidence for a causal role of the IL-6 pathway in the development of atherosclerosis, raising expectations for ongoing trials testing anti-inflammatory strategies for cardiovascular diseases." (PMID 29312959, 2017). "Elevated levels of IL-6 have been linked to multiple age-associated conditions, such as atherosclerosis, dementia and frailty, however causality and pathogenesis is yet to be proven." (PMID 27777599, 2016). "Macrophage-associated cytokines such as TNF-α, IL-1β, and IL-6 have emerged as key factors in the pathogenesis of atherosclerosis." (PMID 27281478, 2016). "Tobacco has been shown to be associated with both subclinical markers of atherosclerosis (hsCRP, interleukin 6, fibrinogen, carotid intima-media thickness, coronary artery calcification, and ankle brachial index) and the incident cardiovascular events in MESA." (PMID 27322410, 2016). "Decreased telomere length has also been associated with atherosclerosis and cardiovascular disease, and is likely to be correlated with interleukin 6 levels." (PMID 27034702, 2016). "In normal individuals or patients with various diseases such as atherosclerosis and undertaken peritoneal dialysis, blood lutein or lutein/zeaxanthin levels were inversely associated with the elevation of IL-6 levels." (PMID 27047687, 2016). "It has been shown that in patients with AS, a high serum IL-6 level is associated with a higher risk of atherosclerosis." (PMID 27527149, 2016). "High levels of tumor necrosis factor (TNF) and IL-6 associated with RA are also significantly associated with the development of atherosclerosis." (PMID 27736998, 2016). "The increased inflammatory activity associated with atherosclerosis and in-stent restenosis is partially brought about by increased levels of proinflammatory cytokines, particularly IL-6." (PMID 25744542, 2015). "Our previous demonstration of associations of high memory and low naive cells with IL-6 and subclinical atherosclerosis implicates chronic adaptive immune activation and loss as an important mechanism in other inflammatory diseases." (PMID 26458065, 2015). "Its activity has been associated with atherosclerosis.Additionally, NF-κB regulates the expression of a number of genes involved in celladhesion and inflammation including IL-6, TNF-α, E-selectin, vascular cell adhesionmolecule-1, ICAM-1, and L-selectin." (PMID 26397969, 2015). "It is IL-6 receptor ‘trans-signalling’ that is thought to underlie the proinflammatory actions of IL-6 in various diseases, including atherosclerosis." (PMID 25744542, 2015). "CD160 engagement by both classical and non-classical MHC-I molecules mediates NK cell cytotoxicity and proinflammatory cytokine production of a unique profile (IFN-γ, TNF-α, and IL-6), all of which have been implicated in atherosclerosis." (PMID 26071079, 2015). "IL-6, an important inflammatory immune reaction medium, is involved in atherosclerosis formation and development, which is an important risk factor for coronary heart disease." (PMID 25667680, 2015). "ET-1 has previously been found to stimulate the release of interleukin-6 and has been implicated in the development of atherosclerosis and vascular dysfunction." (PMID 26823980, 2015). "The administration of IL-6 to mice susceptible to atherosclerosis and to mice resistant to atherosclerosis receiving a cholesterol-rich diet resulted in atherosclerotic lesions developing only in mice susceptible to atherosclerosis." (PMID 25839035, 2015). "Circulating concentrations of novel CVD risk biomarkers including interleukin-6 and interleukin-5 adipokines were mostly similarly associated with both endothelial activation and atherosclerosis amongst African black and white RA patients." (PMID 25157371, 2014). "The association between IL-6 and ischemic heart disease is well documented and is substantially attributable to the effects of IL-6 on atherosclerosis plaque formation." (PMID 25442699, 2014).